GSK3B (glycogen synthase kinase 3 beta)
Diseases named in the same sentence as GSK3B in open-access papers (continued):
Sharing a sentence is not in itself a finding about the gene and the disease.
oral cancer (continued). "An inverse correlation between cyclin D1 and GSK3β expression has been reported in oral cancer." (PMID 20537194, 2010). "In addition, in oral cancer cells, blocking PI3K/Akt signaling causes more cells to undergo apoptosis; this effect is reversed by the use of a GSK3β inhibitor." (PMID 20537194, 2010). "The evidence suggests a link between key players in oral cancer that control transcription, accelerated cell cycle progression, activation of invasion/metastasis and anti-apoptosis, and regulation of these factors by GSK3β." (PMID 20537194, 2010). "Moreover, the major upstream kinases of GSK3β and their oncogenic activation by several etiological agents of oral cancer support this hypothesis." (PMID 20537194, 2010). "GSK3β-mediated signaling could explain numerous molecular disorders specific to oral cancer." (PMID 20537194, 2010). "Therefore, our results suggest that the EGFR signal enhances accumulation of β-catenin in the nuclei of oral cancer cells directly, by phosphorylation of β-catenin, and indirectly, by stabilization of β-catenin through phorsphorylation and inhibition of GSK-3β." (PMID 20302655, 2010). "We used two strains of cultured oral cancer cells, one with reduced EGFR expression (OECM1 cells) and one with elevated EGFR expression (SAS cells), and measured downstream effects, such as phosphorylation of β-catenin and GSK-3β, association of β-catenin with E-cadherin, and target gene regulation." (PMID 20302655, 2010). "In oral cancer, CD44 governs the invasive and metastatic potential of cells, especially the cancer stem cell sub-population by modulating the PI3K/Akt/GSK3β pathway." (PMID 37316916, 2023). "Crosstalk between Raf-MEK-ERK and PI3K-Akt-GSK3β signaling can promote chemoresistance, progression and stemness through regulating the expression of CD44 in oral cancer." (PMID 34949193, 2021). "The present study was designed to investigate the effect of nimbolide on autophagy and the time point at which the phosphorylation status of GSK-3β and PI3K dictate the choice between autophagy and apoptosis in SCC131 and SCC4 oral cancer cells." (PMID 30352996, 2018). "Therefore, it is logical to hypothesize that the inactivation of GSK3β contributes to oral cancer." (PMID 20537194, 2010). "Therefore, the role of the p90RSK/GSK3β pathway might be important in oral cancer." (PMID 20537194, 2010). "Our findings revealed that targeting DNMT1 in oral cancer cells resulted in near-complete genome-wide DNA hypomethylation, triggering the dual attenuation of PI3K-AKT and CDK2-Rb and collaborative phosphorylation of GSK3β." (PMID 38755637, 2024). "In the present study, we investigated the effect of nimbolide on autophagy and the time point at which the phosphorylation status of GSK-3β and PI3K dictates the choice between autophagy and apoptosis in nimbolide treated SCC131 and SCC4 oral cancer cell lines." (PMID 30352996, 2018). "The inactivation of GSK3β in OSCC may behave like an oncogene, and its gradual/sustained inactivation may promote oral cancer." (PMID 20537194, 2010). "Additionally, ICAM-1 has been reported to interact with many signaling pathways in human diseases, such as ICAM-1-PI3K/Akt/GSK-3β/GATA-6 pathway in atheroscherosis, ICAM-1-IL-6/AKT/STAT3/NF-κB pathway in chronic obstructive pulmonary disease, and ICAM-1-PGE2/EP1 pathway in oral cancer." (PMID 33506255, 2021).
diabetic cardiomyopathy (18 papers, 2011 to 2025). Diabetic cardiomyopathy is a disorder of the heart muscle in people with diabetes. "Similar findings have been reported in a diabetic animal model showing that antioxidant treatment causes an inactivation of GSK3β, leading to prevention of diabetic cardiomyopathy." (PMID 26918336, 2016). "In the present study, diabetic cardiomyopathy is characterized by an decrease in the phosphorylation state of Akt and GSK-3β, which was associated with augmented cardiac inflammation as evidenced by increased NF-κB phosphorylation and TNF-α, IL-6 expression, as well as increased MPO activity." (PMID 21232147, 2011). "Studies have shown that IGF-1 can effectively improve diabetic cardiomyopathy through its antioxidant and anti-inflammatory effects, as well as by activating the Akt/GSK-3β signaling pathway." (PMID 40161384, 2025). "GSK-3β is a pro-apoptotic kinase, which is a pivotal player in diabetic cardiomyopathy and myocardial IRI." (PMID 34712418, 2021). "ALDH2 has a role in the protection against diabetic cardiomyopathy, possibly via an Akt-GSK3b-mediated route, lending ALDH2 therapeutic promise in the management of diabetic complications." (PMID 31234367, 2019). "Inhibition of GSK3β via the over-expression of metallothionine has been shown to attenuate the development of ventricular remodeling in the development of diabetic cardiomyopathy." (PMID 30978208, 2019). "Akt and glycogen synthase kinase (GSK)-3β are reported to be decreased in diabetic cardiomyopathy, along with increases in fibrosis and inflammation." (PMID 26242235, 2015). "In conclusion, our results demonstrate that Emo provides potent protection against diabetic cardiomyopathy in a rat model by regulating the AKT/GSK-3β signaling pathway." (PMID 25232702, 2014). "The present study was to investigate the role of kinin B2 receptor-Akt-glycogen synthase kinase (GSK)-3β signalling pathway in mediating the protective effects of tanshinone IIA (TSN) on diabetic cardiomyopathy." (PMID 21232147, 2011). "In contrast, the significant regulation of the diabetic cardiomyopathy gene Gsk3b (glycogen synthase kinase 3 beta, x = −1.490, CUT = 1.341) and the purine metabolism gene Gucy1b2 (guanylate cyclase 1, soluble, beta 2; x = 1.490, CUT = 1.426) would have been neglected." (PMID 38534766, 2024). "Moreover, certain exogenous drugs like empagliflozin have demonstrated the ability to activate the AMPK/glycogen synthase kinase 3 beta (GSK3β) signaling pathway in diabetic cardiomyopathy." (PMID 37671091, 2023). "We noted that activation of the PI3K/Akt/GSK3β signalling pathway induced by LDR in the diabetic hearts occurred in a dose‐dependent manner, so whether activation of Akt signalling itself was a component of LDR‐induced cardiac protection against diabetic cardiomyopathy was investigated in vitro." (PMID 26991817, 2016).
Hepatic steatosis (18 papers, 2012 to 2025). Steatosis is a term used to denote lipid accumulation within hepatocytes. "In the present study, we found that liver biliverdin reductase A (BVRA) inhibits the protective effect of glycogen synthase kinase 3 (GSK3β) on hepatic steatosis by enhancing serine 9 phosphorylation." (PMID 33204683, 2020). "The phosphorylation levels of Akt and GSK3β were significantly decreased in the cows with fatty liver, which further indicated that cows with fatty liver exhibited impaired insulin signaling." (PMID 29882814, 2018). "In particular, we explored the effects of PF on improving fatty liver and IR in NAFLD rats based on its effects on the lipid metabolism-associated regulators and insulin-associated IRS/Akt/GSK3β pathway." (PMID 28300221, 2017). "Furthermore, the GSK3β-CREBH-DGAT1 axis has the potential to serve as a therapeutic target for the treatment of fatty liver disease and improve the quality and safety of aquatic products." (PMID 38641731, 2024). "In addition, several researchers found that APS enhanced insulin sensitivity and ameliorated hepatic steatosis by regulating the expression of GSK3β, although these results were contradictory." (PMID 36059978, 2022). "In addition, the reduced expression level of GSK3β in the liver presents concurrently with the amelioration of hepatic steatosis and fibrosis, indicating the miR-29a/GSK3β pathway acts significantly in the hepatoprotective effect." (PMID 32961796, 2020). "Furthermore, the phosphorylation levels of the GSK‐3β were decreased upon FFA stimulation, suggesting this key mental disease‐associated factor 24 was indeed involved in the pathogenesis of hepatic steatosis." (PMID 31033195, 2019). "In MetS, BVRA protects against hepatic steatosis by inhibiting GSK-3β." (PMID 28531131, 2017). "This was determined by evaluating hepatic steatosis severity and the phosphorylation levels of key proteins in the hepatic insulin signaling pathway (PI3K/AKT/GSK3β)." (PMID 38599845, 2024). "Mechanistically, KAL induced hepatic steatosis and NASH by down-regulating ATGL and CGI-58 by LRP6/Gɑs/PKA/GSK3β pathway." (PMID 38472195, 2024). "Hepatic steatosis was attenuated by TM5441 along with improvement of hepatic insulin sensitivity presented by decreased p-JNK along with increased p-Akt and p-GSK3β." (PMID 29163785, 2017). "Importantly, the Akt and GSK3β phosphorylation levels, protein levels of PGC-1α and four of the five representative subunits of oxidative phosphorylation (OXPHOS) were significantly decreased in cows with fatty liver using Western Blot analysis." (PMID 29882814, 2018).
Parkinson’s (18 papers, 2008 to 2025). "Thus, GSK-3β is robustly activated in MPTP models of Parkinsonism, in transgenic mice overexpressing α-SYN, and in the striatum of PD patients." (PMID 34609698, 2021).
viral infection (18 papers, 2012 to 2026). "During viral infection, GSK3β is known to associate with TBK1 and promote self-association and autophosphorylation at S172; however, the effect of GSK3β on TBK1 is independent of its kinase activity." (PMID 26656453, 2015). "GSK3β activity during modulation of the inflammatory response induced by bacterial, parasitic, LPS, viral infection, and viral-PAMP stimuli." (PMID 34017345, 2021). "The involvement of PI3K/Akt signalling pathway proteins including GSK3β and severalother downstream effectors in viral infections has been described." (PMID 32130369, 2020). "GSK3β, a proteinkinase downstream of PI3K/Akt, gets inactivated upon activation of thePI3K/Akt pathway, and its association with viral infections has beenrecently established." (PMID 32130369, 2020). "Aside well-described roles of GSK3β in processof glucose metabolism and different cellular processes, growing evidence supportsits participation in induction of apoptosis in some viral infections such as HIV-1,VZV, HCV, among others." (PMID 32130369, 2020). "Recent studies have unearthed GSK3β’s role in viral infections through its alteration of viral entry, replication and egress." (PMID 33324423, 2020). "Hence, future directions for drug development targeting GSK3β should emphasize the design of selective inhibitors, the investigation of combination therapies and the investigation of role of GSK3β in various diseases, including cancer and viral infections." (PMID 41190025, 2025). "Moreover, the exploration of role of GSK3β in viral infections, such as COVID-19, opens new avenues for drug development." (PMID 41190025, 2025). "A singular viral marker may be insufficient to accurately reflect viral infection load, particularly if the marker has potential target-marker interaction, as in the case of GSK3β and the N protein." (PMID 36508083, 2022). "GSK3β has additionally been shown to play a role in bacterial and viral infection control." (PMID 36508083, 2022). "This indicates that beneficial effects of GSK3β inhibitors in viral infections could be due to the activation of the immune system cells." (PMID 34017345, 2021). "It is likely that during viral infection the inhibited or activated state of GSK3β may promote inflammation, a similar situation to those observed in bacterial infections." (PMID 34017345, 2021). "Hence inhibition of GSK-3β in the context of encephalitic viral infections has been useful in a neuroprotective capacity." (PMID 22496857, 2012). "GSK-3β binds to TBK1 and enhances TBK1 activity by facilitating its auto-phosphorylation at Ser172 during viral infection, which then up-regulates type I IFN responses." (PMID 32849638, 2020). "Instead, Gsk3β mediates oligomerization and auto-phosphorylation of TBK1, a kinase responsible for IRF3 phosphorylation after viral infection." (PMID 28754897, 2017). "GSK3β is an upstream kinase regulating PD-1 transcription, and the use of GSK3β inhibitors in vivo downregulates PD-1 and enhances CTL clearance of viral infections." (PMID 28018344, 2016). "Phosphorylation of GSK3β-Ser9 was observed at the early stages of infection;neither did treatment with small molecule inhibitors nor pre-treatment priorto viral infection of GSK3β reduce viral titres of the supernatant at thesetime points." (PMID 32130369, 2020). "GSK-3β binds to TBK1 and induces TBK1 phosphorylation upon viral infection." (PMID 32849638, 2020). "Additionally, the level of cellular glycogen synthase kinase 3β (GSK3β) is downregulated by SSS exposure and treatment with a specific GSK3β inhibitor recapitulates the effects of SSS exposure on CAR expression and viral infection." (PMID 23166798, 2012). "After viral infection of INS-1 832/13 cells, we validated their efficacy by showing that both GSK3β-specific shRNA sequences efficiently decreased mRNA levels of GSK3β, without alterating the levels of GSK3α mRNAs." (PMID 34876563, 2021).
breast tumor (17 papers, 2012 to 2025). "C/EBPδ knock out (C/EBPδ-KO) breast tumor cells exhibit reduced Akt activity and decreased Ser9 phosphorylation of GSK-3β, which causes increased expression of FBXW7 downstream of GSK-3β." (PMID 37658431, 2023). "Moreover, analyses of TCGA tumour data demonstrated that GSK3α and GSK3β mRNA levels are specifically increased in BRCA1/2-mutated breast tumours, suggesting GSK3 as a potential clinical target for tumours lacking BRCA function." (PMID 34389725, 2021). "The levels of the hallmarks of cell proliferation and angiogenesis involved in IGF-1/PI3K/Akt/GSK3β/β-catenin signaling pathway molecules were upregulated in obese rat breast tumors compared to lean rats." (PMID 37511200, 2023). "To examine the clinical relevance of GSK3β, we analyzed Oncomine data and found GSK3β is significantly overexpressed in breast tumors in comparison with normal breast tissue in multiple datasets (Ma dataset, Richardson dataset 2, and TCGA)." (PMID 30845991, 2019). "Available evidence suggests that GSK-3β may function as a “tumor suppressor” for certain types of tumors such as skin and breast tumors." (PMID 40157890, 2025). "We next examined whether in vivo pharmacological inhibition of GSK3B using lithium affects PARPi-induced tumor control in mouse allogenic orthotopic breast tumor." (PMID 41243969, 2025). "This suggests that GSK-3β may influence cell activity by regulating mitochondrial function and oxidative stress in canine breast tumor cells." (PMID 40643495, 2025). "It is notable that the shear stress-dependent TIC formation of breast tumor cells depends on ROS/NO generation and downregulation of the ERK and GSK3β pathways." (PMID 30651129, 2019). "To examine the pathological relevance of EZH2 regulation by GSK3β, we analyzed correlation between the activity of GSK3β and the enzymatic activity of EZH2 in human breast tumor specimens." (PMID 27494834, 2016). "It was shown that GSK-3β is a positive regulatory enzyme to promote cancer cell proliferation and survival and based on shreds of evidence, 15-LOX might be served by GSK-3β as a downstream mediator to regulate feroptosis in breast tumor cells." (PMID 34838055, 2021).
liver fibrosis (16 papers, 2017 to 2025). "We found that circABHD3 facilitated the decay of YPEL3 mRNA in a m6A/YTHDF2 dependent manner, leading to GSK-3β downregulation and inactivation of β-catenin signaling in liver fibrosis." (PMID 40100806, 2025). "Vice versa, the application of the tetracyclic triterpenoid actein dose-dependently reduced both p-GSK3β-Ser9 and hepatic fibrosis." (PMID 39125833, 2024). "Another study reported that the prevention of CCl4–induced liver fibrosis by the iridoid glycoside hastatoside appears to depend on its ability to bind to GSK3β and enhance its activity." (PMID 39125833, 2024). "The bioflavonoid morin, either protectively or therapeutically applied, significantly ameliorated DEN-dependent liver fibrosis and decreased GSK3β expression." (PMID 39125833, 2024). "As the PI3K/AKT/GSK-3β signaling pathway is closely related to the development of liver fibrosis, this study explored the effects of SAL in bile duct ligation-induced cholestatic liver fibrosis using in vivo experiments." (PMID 38808258, 2024). "SAL inhibits HSC activation through the PI3K/AKT/GSK-3β pathway and improves intestinal flora distribution, thereby protecting and reversing the progression of hepatic fibrosis." (PMID 38808258, 2024). "Morin (3, 5, 7, 2′, 4′-pentahydroxyflavone), a natural bioflavonoid, inhibits HSC activation by directly downregulating GSK-3β gene expression, resulting in attenuated liver fibrosis." (PMID 33052244, 2020). "The GSK3β inhibitor effect was unexpected, since modulating Wnt/β-catenin signaling has had variable effects on liver fibrosis in mouse models; in a murine bile duct ligation model, GSK3β inhibitor administration increased the extent of liver fibrosis." (PMID 39656528, 2024). "GSTA3 inhibited hepatic stellate cells (HSCs) activation and liver fibrosis through suppression of the MAPK and GSK-3β signaling pathways by regulating OS." (PMID 38069262, 2023). "This study was the first to validate the reduction in BMSCs in rat liver fibrosis and found that BMSC treatment exerted antifibrotic effects by activating the expression of GSK3β and inhibiting the Wnt3a/β-catenin signalling pathway." (PMID 35440002, 2022). "Studies have shown that GSK-3β is involved in HSC activation, transdifferentiation, and subsequent proliferative processes during liver fibrosis." (PMID 33052244, 2020). "Through activating GSK-3β, actein treatment significantly reduces the levels of fibrosis markers, including α-SMA, COLI, and COLIII, thereby preventing the development of liver fibrosis in high-fat diet-induced mice." (PMID 33052244, 2020). "We demonstrated firstly that GSTA3 inhibited HSCs activation and liver fibrosis through suppression of the MAPK and GSK-3β signaling pathways." (PMID 31443720, 2019). "Similarly, TGF-β1 induces ERK activation, leading to the inactivation of GSK-3β, followed by increased stability of β-Catenin, which contributes to HSC activation and liver fibrosis." (PMID 33052244, 2020). "To investigate whether enhanced expression of Tb4 increased Hh signaling and contributed to the excessive hepatic fibrosis in the CCl4-treated Tb4-Tg mice, we examined the expression levels of ILK, GSK3B and Hh signaling." (PMID 28630423, 2017). "In summary, live-cell imaging of human microHOs has identified GSK3β and p38 MAPK inhibitors as potential new therapies for liver fibrosis, and it is likely that other new therapies and their mechanism(s) of action could subsequently be identified using this system." (PMID 39656528, 2024). "Given that GSK3B is one of the targets of ILK29, 46, it is possible that TB4-dependent activation of ILK and concomitant repression of pGSK3B increases Hh signaling by promoting the activation of SMO-GLI2, resulting in the activation of quiescent HSCs during liver fibrosis." (PMID 28630423, 2017).